KLF5 (KLF transcription factor 5)
Diseases named in the same sentence as KLF5 in open-access papers (continued):
Sharing a sentence is not in itself a finding about the gene and the disease.
colon carcinoma (35 papers, 2011 to 2025). "To confirm the association between chr13q gain and KLF5 expression and dependency, we next turned to an isogenic system of human colon cancer cells (DLD1) into which trisomy 13 had been introduced (DLD1-Ts13)." (PMID 38622679, 2024). "Our analysis revealed that KLF5 expression was significantly elevated in tumor tissues compared to adjacent normal tissues in cases of colon cancer, ovarian cancer, and cervical cancer." (PMID 39827156, 2025). "We also identify the importance of tissue-selective features and demonstrate them experimentally, revealing KLF5 as an important driver for chr13q gain in colon cancer." (PMID 38622679, 2024). "The infiltration levels of all TIICs, including B cells, CD4+T cells, CD8+ T cells, neutrophils, macrophages, and dendritic cells, were favourably linked with the expression of KLF3, KLF5, and KLF6 in colon cancer." (PMID 35345512, 2022). "The inhibition of KLF5 by miR‐153 suppresses cellular invasion in laryngeal squamous cell carcinoma, while miR-4711-5p reduces KLF5 mRNA and protein expression in colon cancer cells." (PMID 35836107, 2022). "KLF5 has been reported to regulate intestinal epithelial cell proliferation, particularly in the context of colon cancer." (PMID 35779631, 2022). "We searched for candidate microRNAs (miRNAs) that inhibited KLF5 expression by in silico analyses and screened them in colon cancer cell lines." (PMID 32066912, 2020). "In contrast to these findings, KLF5 has been shown to have growth inhibitory properties in colon cancer‐derived cells." (PMID 30478887, 2019). "To evaluate the potential of the PrPc/FOXO3a/KLF5 axis to be prognostic in aggressive colon cancer, we examined a cohort of 46 Grade 3 patients for survival rates based on expression." (PMID 30478887, 2019). "Another study confirmed that KLF5 knockdown inhibited β-catenin/TCF transcriptional activity in colon cancer cells." (PMID 29463902, 2018). "Multicellular tumor spheroid (MCTS) formation in HT-29 colon carcinoma cells required high KLF5 expression, and tumor formation can be inhibited by KLF5 knockdown." (PMID 29312609, 2017). "Taken together, we suggest that YAP1/KLF5-activated Ascl2 expression in colon cancer progenitor cells confers their self-renewability." (PMID 29312609, 2017). "Small molecules show antiproliferative activity in colon cancer through KLF5-expression inhibition, thus SHH implication in gastric carcinogenesis could be further evaluated for targeted therapy." (PMID 38542354, 2024). "Overexpression of KLF5 is inversely correlated with the prognosis of colon cancer patients." (PMID 37181807, 2023). "In another two reports, LPA-LPAR2 may facilitate colon cancer proliferation via transcription factor Kruppel-like factor 5 (KLF5) and hypoxia-inducible factor 1α (HIF-1α) activations." (PMID 34209775, 2021). "Additionally, many other driver genes are frequently mutated in colon cancer, such as ARID1A, SOX9, FAM123B, BCL9L, RBM10, CTCF, and KLF5." (PMID 34912802, 2021). "In contrast, overexpression of KLF5 in colon cancer cell shows the opposite effects." (PMID 30271790, 2018). "LPA increases the expression of KLF5 to increase cell proliferation in colon cancer cells, and this LPA-induced KLF5 expression is mediated by LPAR2 and LPAR3." (PMID 36142408, 2022). "A previous high-throughput screening approach identified several novel and potent small molecular inhibitors of KLF5, such as Wortmannin, AG17, and AG879, which inhibit proliferation of colon cancer cell lines." (PMID 31401336, 2019).
colon carcinoma (continued). "LPA2 induces KLF5 expression, and knockdown of KLF5 reduces proliferation of SW480 and HCT116 colon cancer cells by impeding cell cycle." (PMID 31323936, 2019). "Ectopic overexpression of KLF5 indeed stimulated proliferation of normal intestinal epithelium through activation of CCND1, yet in colon cancer cells, proliferation and colony formation capacity were reduced through failure of KLF5 to induce CCND1." (PMID 24429391, 2014). "Importantly, KLF5/COX2-mediated immune profiles display prognostic value in breast and colon cancer." (PMID 36923542, 2023). "Although these genes are found to be overexpressed in several malignant tumours, including gastric and colon cancers, it remains unclear whether the products of FGF9, FLT1 and KLF5 are overexpressed in colorectal intramucosal adenocarcinoma." (PMID 28197804, 2017). "Recently, in an established xenograft mouse model of colon cancer, the drug ML264 efficiently inhibited growth of the tumor within 5 days of treatment by inhibiting the expression of KLF5 and EGR1, a transcriptional activator of KLF5." (PMID 28915599, 2017).
bladder cancer (28 papers, 2009 to 2025). "Klf5 also promotes cell proliferation and tumorigenesis of the TSU-Pr1 human bladder cancer cell line and Klf5 overexpression may be linked to salivary gland tumors." (PMID 20514221, 2009). "KLF5 may be utilized as a diagnostic tool for cancer, a predictor of its progression, and a guide for treatment., with particular promise as a therapeutic target for glioma and bladder cancer." (PMID 41583492, 2025). "We further conducted RT-qPCR to assess the mRNA expression of KLF5, and the result showed that KLF5 was upregulated in bladder cancer cell lines like 5637 and RT113." (PMID 41583492, 2025). "Consistent with the verification results obtained in GBM cell lines, we found that KLF5 knockdown significantly inhibited the ability of bladder cancer cell proliferation and migration." (PMID 41583492, 2025). "Since 5637 possessed the highest KLF5 expression level, we conducted KLF5 knockdown using siRNA in this bladder cancer cell line." (PMID 41583492, 2025). "We performed K–M survival analysis and we found that higher KLF5 expression was correlated with unfavorable prognosis in bladder cancer patients." (PMID 41583492, 2025). "Tetrahydroxycurcumin has been demonstrated to dose‐ and time‐dependently reduce the amount of KLF5 protein in 5637 and WH cells of bladder cancer, indicating a post‐transcriptional regulation mechanism without altering mRNA expression." (PMID 41179371, 2025). "Analysis of KLF5 copy number variation revealed two major patterns: heterozygous amplification, primarily in gastrointestinal, lung adenocarcinoma, and bladder cancers, and heterozygous deletion with a broader distribution across multiple cancer types." (PMID 41583492, 2025). "It was confirmed that miR-5195-3p inhibited the proliferation and invasion of bladder cancer cells by targeting the oncogene KLF5.21 and inhibited the activity of HCT116 cells by inhibiting the expression of TGFβR1, TGFβR2, SMAD3 and SMAD4." (PMID 37328795, 2023). "It is already known that KLF5 is a key controller of cell proliferation, as in bladder cancer, where it regulates cyclin D1 or Cyclin E expression." (PMID 35683018, 2022). "CINP was established as a cofactor of KLF5 crucial for tumor growth in the bladder cancer and HeLa cell lines." (PMID 36591491, 2022). "For example, miR-5195-3p sharply reduced KLF5 to suppress the proliferation and invasion of human bladder cancer cells." (PMID 34793551, 2021). "For example, miR-5195-3p suppressed growth and proliferation of human bladder cancer cells via suppression of Krüppel-like factor 5 (KLF5)." (PMID 34793551, 2021). "For example, miR-5195-3p inhibits the proliferation and invasion of human bladder cancer cells by directly targeting KLF5." (PMID 32943987, 2020). "For example, KLF5 binds to a CCNE1 promoter proximal element in bladder cancer cells and KLF5 increases the expression of Ccnb1 and Mcm2 downstream of oncogenic Ras in fibroblasts." (PMID 32880368, 2020). "On one hand, KLF5 has been demonstrated to be upregulated in some types of human cancers, such as breast and bladder cancer, in which it contributes to tumor progression." (PMID 29898734, 2018). "Curcumin promoted KLF5 (krueppel-like 5) proteasome degradation via down-regulating YAP/TAZ in bladder cancer cells." (PMID 27738325, 2016). "We reported here that in bladder cancer cells, KLF5-VEGFA axis was activated by growth factor EGF and bFGF, PKC agonist PMA and mitogenic lipid LPA, but inhibited by inhibitors of EGFR (AG1478), MEK1/2 (U0126) or PI3K (LY294002)." (PMID 26544730, 2015). "To further clarify roles of KLF5 in bladder cancer, we applied lentivirus-delivered specific shRNA to knockdown KLF5 in these three cell lines." (PMID 26544730, 2015). "Taken together, these data demonstrate that KLF5 regulated bladder cancer angiogenesis through promoting VEGFA expression." (PMID 26544730, 2015).
bladder cancer (continued). "In this study, we found that KLF5 was essential for cancer cell-endothelial cell interaction in vitro and tumor angiogenesis in nude mice based on lentivirus-mediated KLF5 knockdown bladder cancer cell models." (PMID 26544730, 2015). "To further verify the importance of KLF5-regulated VEGFA in bladder cancer angiogenesis, we modified VEGFA concentration in the CMs using VEGFA neutralizing antibody MAB293 or recombinant human VEGF165." (PMID 26544730, 2015). "In conclusion, we reported that knockdown of proliferative factor KLF5 not only suppressed the growth of bladder cancer cells but also impaired bladder cancer cell-endothelial cell interaction." (PMID 26544730, 2015). "Mechanistically, KLF5 exerts these functions as a novel pro-angiogenic factor in bladder cancer by directly regulating the transcription of VEGFA, which is the most prominent factor among the angiogenic cytokines." (PMID 26544730, 2015). "Consistent with our previous studies, KLF5 still played a critical role in the regulation of cell proliferation in bladder cancer cells." (PMID 26544730, 2015). "Given these new findings, the additional roles of KLF5 in other aspects of bladder cancer biology beyond proliferation require to be further investigated." (PMID 26544730, 2015). "Because VEGFA plays predominant roles in tumor angiogenesis, we decide to focus our investigation on the regulation of VEGFA by KLF5 and its roles in bladder cancer angiogenesis." (PMID 26544730, 2015). "KLF5 has been shown to play critical roles in proliferation and tumorigenesis in several cancer types, including bladder cancer." (PMID 25170806, 2014). "In this study, we found that curcumin decreased the proliferation of both 5637 and WH bladder cancer cells, and KLF5 was down-regulated by curcumin." (PMID 25170806, 2014). "The study also suggests potential use of curcumin to target the YAP/TAZ/ KLF5/cyclin D1 axis in bladder cancer treatment." (PMID 25170806, 2014). "Exogenous KLF5 promotes TSU-pr1 bladder cancer cell growth in vitro and in vivo, which is consistent with our results that knockdown of KLF5 leads to the down-regulation of cyclin D1 and a decrease of the cell proliferation of 5637 bladder cancer cells." (PMID 25170806, 2014). "In conclusion, we found that KLF5 promotes the growth of bladder cancer cells and that curcumin suppress the KLF5 protein level in a proteasome-dependent way." (PMID 25170806, 2014). "To further validate its role in pan-cancer, we then focused on the role of KLF5 in bladder cancer." (PMID 41583492, 2025). "Ultimately, experiments were carried out to investigate whether KLF5 could serve as a promising indicator for glioma and bladder cancer." (PMID 41583492, 2025). "We further selected various cell lines of GBM and bladder cancer for functional cellular assays, and the results indicated that KLF5 could serve as a potential biomarker for glioma and bladder cancer." (PMID 41583492, 2025). "The expression of FYN by KLF5 can increase tumor invasion and cell migration in bladder cancer." (PMID 36740671, 2023). "Additionally, KLF5 binds to the FYN promoter region to induce its transcription, and overexpression of FYN improves lamellar pseudopod formation and migration in bladder cancer cells in which expression of KLF5 is reduced." (PMID 36740671, 2023). "Additionally, a recent report shows that Kruppel-like Factor 5 (KLF5), a known transcriptional activator in bladder cancer, binds to a novel enhancer element within the first intron region of CCNE148." (PMID 32612143, 2020). "Curcumin suppresses bladder cancer cell growth through down-regulating KLF5 expression." (PMID 32025209, 2020). "KLF5 is a known oncogene in bladder cancer that promotes angiogenesis and invasion." (PMID 33408272, 2020). "Curcumin suppresses bladder cancer cell growth by down-regulating KLF5 expression." (PMID 29348684, 2018).
bladder cancer (continued). "It has been reported that exogenous KLF5 expression increased cell cycle transition and up-regulated cyclin D1 in TSU-Pr1 bladder cancer cells, and accelerated degradation of KLF5 protein performed by curcumin impaired tumor growth of bladder cancer cells in vitro and in vivo." (PMID 26544730, 2015). "Taken together, our results suggest that KLF5 may play an important role in the angiogenesis of bladder cancer through regulating VEGFA." (PMID 26544730, 2015). "Furthermore, microarray data profiling of human bladder cancer tissues downloaded from TCGA and GEO database was applied to examine the co-expression of KLF5 and VEGFA." (PMID 26544730, 2015). "Moreover, KLF5 insufficiency abolished the ability of bladder cancer cells to induce neovascularization in rabbit cornea." (PMID 26544730, 2015). "Importantly, KLF5 as well as VEGFA expression was positively correlated with neovascularization (as evaluated by CD31 staining) in bladder cancer tissues." (PMID 26544730, 2015). "In the present study, we found that pro-proliferative factor KLF5 was not only required for bladder cancer cell growth, but also essential for the interaction between bladder cancer cells and endothelial cells in vitro and tumor angiogenesis in the xenografts in nude mice and in rabbit cornea." (PMID 26544730, 2015). "The important roles of YAP and TAZ in maintaining KLF5 protein stability have been shown in other systems, but whether the same mechanism exists in bladder cancer remains to be determined." (PMID 25170806, 2014). "This demonstrated that down-regulation of KLF5 might be essential for curcumin to inhibit bladder cancer cell growth." (PMID 25170806, 2014). "Our in vitro and in vivo results demonstrate that curcumin inhibits the cell growth of bladder cancer at least partially through inhibiting Hippo pathway effectors YAP/TAZ, which induce the accelerated degradation of KLF5 protein and subsequently cause the downregulation of cyclin D1." (PMID 25170806, 2014). "Thus, our data indicates that curcumin promotes KLF5 proteasome-dependent degradation through targeting YAP/TAZ in bladder cancer cells and also suggests the therapeutic potential of curcumin in the treatment of bladder cancer." (PMID 25170806, 2014). "Thus, the YAP/TAZ/KLF5/cyclinD1 axis is important for the growth of bladder cancer, and it is a potential therapeutic target for curcumin and other chemicals in cancer treatment." (PMID 25170806, 2014). "Thus, our study connected YAP and KLF5 in bladder cancer, and the pro-proliferative YAP/TAZ/KLF5/cyclin D1 axis was also revealed." (PMID 25170806, 2014). "Additionally, Curcumin inhibits KLF5 expression through YAP/TAZ in bladder cancer cell lines." (PMID 28437471, 2017). "Thus, the context-dependent transcription factor KLF5 may exert different functions other than tumor angiogenesis in these two types of bladder cancers, which is needed to be further clarified in the future." (PMID 26544730, 2015). "Because KLF5 is a DNA-binding protein and usually promotes transcription of multiple target genes, we assume that one or more angiogenic factors may be involved in the interactions between bladder cancer cells and HUVECs after KLF5 knockdown." (PMID 26544730, 2015). "However, our studies in bladder cancer all support KLF5 as a pro-proliferative factor." (PMID 26544730, 2015). "Thus further study may be needed to uncover the roles of PDGFA in KLF5-regulated angiogenesis in bladder cancer." (PMID 26544730, 2015). "Thus, clinical evidence above supports that KLF5 might play roles in angiogenesis of human bladder cancer through regulating VEGFA expression." (PMID 26544730, 2015). "Therefore, as an important growth-promoting gene, KLF5 could be a candidate target for bladder cancer treatment, and modulating its degradation will be an efficient approach to inhibit KLF5." (PMID 25170806, 2014). "Therefore, downregulation of KLF5 may be essential for curcumin to inhibit bladder cancer cell growth." (PMID 25170806, 2014).